CXCR4 (C-X-C motif chemokine receptor 4)
Diseases named in the same sentence as CXCR4 in open-access papers (continued):
Sharing a sentence is not in itself a finding about the gene and the disease.
tumor (continued). "It has been reported that hypoxia, particularly HIF-1α, may promote the expression of CXCR4 and activate the SDF-1α/CXCR4 signaling axis, contributing to tumor cell invasion and metastasis." (PMID 31336612, 2019). "CXCR4 depletion in those myeloid cells recovers the tumor-killing capacity of NK cells." (PMID 31474975, 2019). "Therefore, down-regulation of the expression of CXCR4 in cancer cells is a potential therapeutic strategy for inhibiting primary tumor growth and metastasis of TNBC." (PMID 32047724, 2019). "We hypothesized that the CXCR4 antagonist Pep R54 plus anti-PD-1 simultaneously inhibits two core pathways of tumor proliferation, P-ERK/pAKT and p4EBP1." (PMID 31661001, 2019). "This approach tested whether blocking CXCR4 could break the resistance of the tumor to anti-angiogenic therapy." (PMID 30813533, 2019). "MMP-10 contributes to HCC development, participating in tumor angiogenesis, growth, and lung dissemination, induced by hypoxia, an increased CXCR4 expression, stromal-derived factor-1, and increased C-Jun transcriptional activity, resulting in the EMT of HCC cells." (PMID 31886121, 2019). "Therefore, CXCL12/CXCR4/PI3K/Akt signaling pathway has become a hot topic in tumor research and also provides a specifc target spot for cancer treatment." (PMID 31500630, 2019). "In our model, CXCR4 antagonism induced tumor necrosis along with hemorrhage." (PMID 31336612, 2019). "We identified CXCR4 as an indirect target of MDMX in the context of tumor stroma communication." (PMID 31489110, 2019). "Therefore, it would be interesting to extend the findings of this study by investigating the impact of CXCR4 on mechanisms involved in rituximab-induced depletion of tumor cells in an in vivo model system." (PMID 30774774, 2019). "However, CXCR4 signaling in the tumor microenvironment also plays a central role in cancer and further investigations are needed to fully understand its contribution." (PMID 30787324, 2019). "Therapeutic targeting of CXCR4 on tumor cells could be an effective strategy to limit tumor cell growth and metastasis." (PMID 30787324, 2019). "Notably, CXCR4 inhibition is not only acting on tumor cells but is also promoting antitumoral T cell responses." (PMID 30894861, 2019). "Moreover, the participation of the SDF-1/CXCR4 axis in tumor neovascularization through Vascular Endothelial Growth Factor (VEGF)-dependent and -independent mechanisms have been reported." (PMID 31336612, 2019). "Therefore, interruption of cell trafficking by disrupting CXCR4 signalling from the tumour microenvironment is a potential therapy in PTCL." (PMID 30242208, 2018). "As compared to free oligo‐FdU, repeated T22‐GFP‐H6‐FdU administration, in cell line and patient‐derived CRC mouse models, blocks CXCR4+ tumor emboli intravasation in colonic peri‐tumoral vessels and completely prevents metastases development in a high percent of mice." (PMID 30190334, 2018). "Thus, in both, the SW1417 and the M5 CRC models CXCR4+ cancer cells behave as cancer stem cells since their selective elimination reduces their tumor re‐initiation capacity." (PMID 30190334, 2018). "Although some specific markers have been used to identify or purify CSCs, e.g. CD133 or CXCR4 in PrC, it is gradually realized that a single marker or combined a few markers is not sufficient to allow definition and purification of CSCs in tumor." (PMID 30408771, 2018). "Next, we aimed to understand whether tumor expression of CXCR4 and CXCL12 may significantly contribute to serum CXCL12 levels." (PMID 30012106, 2018). "Several tumor-promoting genes such as CXCR4, LSH, MMP9, and hypoxia-inducible factor (HIF)-1α are thought to contribute to radioresistance, and their elevated expression is consistent with their proposed role in cancer progression, metastasis, and radiotherapy." (PMID 29706625, 2018). "In addition, several groups reported an influence of the SDF-1/CXCR4 axis on intratumoral immune cell subsets and anti-tumor immune response." (PMID 30622535, 2018).
tumor (continued). "In this paper, the results of gene transcriptome sequencing, qTR-PCR, Western blotting, cytoimmunofluorescence and immunohistochemistry show that both SDF1 and CXCR4 are present in different tumor cells and even normal liver cells in vitro and in vivo before and after AnnexinA7 regulation." (PMID 29783989, 2018). "Thus, inhibition of Tregs by blocking SDF-1/CXCR4 is one of the major rationales for a better anti-tumor immune response via CXCR4 inhibition." (PMID 30622535, 2018). "Hence, it is possible that early tumor cell-fibroblastic stromal cell interactions dependent on the CXCL12/CXCR4 pathway govern tumor propagation from few malignant cells under both primary and metastatic conditions." (PMID 29632733, 2018). "Together, these studies strongly suggest that tumor cells may indeed benefit from an autocrine CXCL12/CXCR4 loop in the tumor microenvironment and that high CXCL12 expression in lymph nodes may indeed promote the metastasis of CXCR4 expressing cells." (PMID 30257500, 2018). "In addition, Nef-M1, a CXCR4 antagonist peptide, also showed good therapeutic potential for inhibiting tumor angiogenesis and the oncogenic epithelial-to-mesenchymal transition process in patient derived xenographs." (PMID 30012106, 2018). "Given the involvement of CXCR4 in tumor cell migration to many different organs, oral administration of CXCR4 inhibitors could be particularly efficient." (PMID 30420855, 2018). "Our experiments show that the co-expression levels of SDF1/CXCR4 in F/P cells in vitro and corresponding tumor tissues in vivo are higher than those in normal liver cells and normal liver tissue at cDNA, mRNA and protein levels as well as cytoimmunofluorescence and immunohistochemistry intensities." (PMID 29783989, 2018). "Moreover, CXCR4 expression is higher in NB tumor cells from patients with BM metastases compared to those with localized tumors." (PMID 30149659, 2018). "The CXCL12 and CXCR4 axis plays a role in the metastatic homing of tumour cells." (PMID 29887884, 2018). "From the results, we speculated that CD164 was a tumor promoter which could promote the progression of several carcinomas possibly by regulating CXCR4 relevant proteins and activating CXCR4/AKT signaling pathway." (PMID 30022623, 2018). "They performed PET studies in nude mice bearing bilateral (CXCR4+ and CXCR4−) PC3 xenograft tumours and showed excellent tumour targeting, a sevenfold improvement over existing 18F-fluorinated ligands reported to date resulting in high tumour to background ratios." (PMID 29725717, 2018). "In addition, administering the CXCR4 antagonist AMD3100 to mice prior to the nanoconjugate completely blocked its tumor uptake as well as its internalization in CXCR4+ cancer cells." (PMID 30190334, 2018). "Explicitly, 85% of CXCR4-expressing primary tumours raised peritoneal metastases." (PMID 29867026, 2018). "In the last decade, several preclinical studies in glioma models have shown that the impairment of the CXCL12/CXCR4 signaling using specific antagonists reduces tumor growth, angiogenesis, and recurrence, suggesting that this approach represents a promising strategy for GB therapy." (PMID 30123112, 2018). "However, there are no substantial studies elaborating upon the detailed mechanism(s) of CXCR4 over-expression in tumor cells." (PMID 30564115, 2018). "Hypoxia also induces the expression of SDF1/CXCR4 in tumor cells." (PMID 29783989, 2018). "Alternative approaches may also include expansion of intratumoral DCs following CXCR4 antagonist-armed oncolytic virotherapy treatment to increase phagocytic clearance of tumor cell debris after virally-mediated cytolysis." (PMID 30149659, 2018).
tumor (continued). "The epidermal growth factor receptor (EFGR) mutation was closely related to the invasion and metastasis of lung adenocarcinoma and the biological axis of CXCR4/CXCL12 (chemokine receptor 4/chemokine ligand 12) played an important role in the organ-specific metastasis of the tumor." (PMID 30037369, 2018). "We next sought to investigate whether CXCR4 expression is altered in splenocytes from FLT-3 ligand-induced tumor mice." (PMID 30489627, 2018). "Importantly, radiation-modulated SDF-1/CXCR4 signaling has been shown to stimulate tumor re-growth, EMT, migration, invasiveness and metastases, as well as homing of hematopoietic progenitor cells and accelerated vasculogenesis." (PMID 30622535, 2018). "Such interactions might include upregulation of CXCR4 by different factors (e.g., estradiol), tumor cell-stromal cell interactions, recruitment of CXCR4-positive immune cells to tumor sites inducing local inflammatory response." (PMID 30191351, 2018). "To date, oncology pre-clinical in vivo studies for CXCR4-targeting antibodies consist of human CXCR4+ tumor cells implanted or infused in immunocompromised mice or the use of anti-mouse CXCR4 “surrogate” antibodies in the case of mouse syngeneic tumors and tumor-prone genetic models." (PMID 29554149, 2018). "Moreover, CXCL12 produced within the tumor can attract CXCR4+ Treg, MDSC and plasmacytoid dendritic cells (pDC), potentiating the tumor-promoting effect." (PMID 30319622, 2018). "A study on the role of CXCR4 in EOC metastases showed that downregulation of CXCR4 by short hairpin RNA (shRNA) resulted in a robust reduction of the circulating tumor cells, suggesting a possible role of the stromal cell-derived factor 1 (SDF1)/CXCR4 axis in the hematogenous route of dissemination." (PMID 30445726, 2018). "The role of CXCL12/CXCR4 signaling in tumor cell motility and invasion is well established." (PMID 29930538, 2018). "CXCL12 may serve to prevent adequate T and CAR-T cell penetration into or recognition of the tumor by forming a barrier of CXCR4+ immunosuppressive cells." (PMID 30420856, 2018). "However, its specific role is still a controversial issue, probably due to the tumor heterogeneity but also because of the different techniques, methodologies and protocols used in quantification of CXCR4 and CXCL12 expression." (PMID 30012106, 2018). "CXCR4 in vivo imaging in these cases might have a benefit to provide longitudinal spatiotemporal information on tumor progression/metastasis during targeted estrogen deprivation therapy." (PMID 30191351, 2018). "Ubiquitin is, due to cell death and necrosis, present in non-physiologically high, extracellular concentrations in tumor tissue and could therefore be the relevant ligand for CXCR4 in a tumor." (PMID 29721166, 2018). "It is, therefore, tempting to speculate that SDF-1−/CXCR4+ tumor cells are particularly prone to metastasize." (PMID 30622535, 2018). "Several studies indicated that intimate contact between CXCR4 expressed on tumor cells and SDF1α in the niche might represent a key mechanism for metastatic spread and tumor resistance." (PMID 29382856, 2018). "In tumor areas with necrosis, angiogenesis, and invasion, the GSCs express mainly the CXCR4." (PMID 30123112, 2018). "Blockade of CXCR4 in most tumor models prevents OCL maturation and osteolysis." (PMID 29930538, 2018). "Their recruitment to the tumor sites is mediated by the CXCL12/CXCR4 axis, and might be enhanced by the chemokines known to form a complex with CXCL12." (PMID 30319638, 2018). "Mammalian CXCL12/CXCR4 signaling is involved in many cellular programs ranging from directed cell migration and organ development to self-renewal of hematopoietic stem cells and tumor metastasis." (PMID 30202007, 2018). "In addition, bone marrow-derived CXCR4+ vascular cells can be recruited by CXCL12-expressing tumor/stromal cells and contribute to a microenvironment that supports tumor angiogenesis." (PMID 29554149, 2018).
tumor (continued). "The ability of MYC and CXCL12/CXCR4 signaling to maintain a high glycolytic flux may also allow tumor cells to invade tissues with low-oxygen tension." (PMID 30202007, 2018). "The stromal cell-derived fractor-1 (SDF-1) or CXCL12/CXCR4 axis, critical for trafficking/homing of hematopoietic stem cells, represents an important functional axis in many solid tumors involved in the mechanism of tumor metastasis." (PMID 29389895, 2018). "A study by Goda S. and colleagues may in part explain how increased CXCR4 surface levels can facilitate NK cells to cross the bridge connecting the stroma and the tumor parenchyma compartments." (PMID 30364222, 2018). "Therefore, the nanoconjugate achieves not only selective tumor biodistribution, but also its specific internalization into target CXCR4+ cancer cells, in a CXCR4‐dependent manner." (PMID 30190334, 2018). "Additionally, we revealed that protumor TAMs and CXCR4-positive cancer cells were frequently localized in the same areas of the primary tumor." (PMID 29849822, 2018). "Moreover, another antagonist of CXCR4, the peptide R, decreases the tumor mass of GB-xenotransplanted cells and reduces the CD11/CD68-positive cells in peritumoral zone of the tumor." (PMID 30123112, 2018). "CXCR4 levels may be useful as a predictive marker of tumor development, growth, metastasis and a therapeutic target." (PMID 29774098, 2018). "CXCL12 and CXCR4 have been identified with significantly elevated levels in various malignancies and correlate with the survival, proliferation, angiogenesis, and the metastasis of tumour cells." (PMID 29887884, 2018). "Moreover, CXCR4 is also involved in the recruitment of suppressive immune cells, such as mast cells in the tumor microenvironment." (PMID 30420855, 2018). "CXCR4 mRNA expression was inversely correlated in tumours with a lymphatic invasion." (PMID 29887884, 2018). "Tumor-initiating cells enriched for CD133/CXCR4/EpCAM are highly metastatic." (PMID 30486409, 2018). "Mobilization of HSCs, a significant increase of immune and progenitor cells in the periphery that are able to migrate into the tumor and the selective targeting of Treg cells in the tumor lesion provide the rationale for an increased anti-tumor immune response upon CXCR4 inhibition." (PMID 30622535, 2018). "We also evaluated whether the delivered FdU could induce DNA damage and caspase‐3‐dependent cell death, triggering the specific elimination of CXCR4+ tumor cells." (PMID 30190334, 2018). "In agreement with our results, several reports indicate that BM‐MSCs secrete high levels of SDF‐1 but express low levels of CXCR4, whereas OS cells release small amounts of SDF‐1 but express elevated levels of CXCR4, crucial to promote the metastatic spread of the tumour to the lung." (PMID 29517849, 2018). "In silico analysis confirmed that the expression of CXCR4 in the primary tumor significantly correlated not only with the expression of its ligand CXCL12 (Spearman's coefficient, rs = 0.4920) but also with the expression of VIM (rs = 0.4779) and CD163 (rs = 0.4853)." (PMID 29849822, 2018). "Taken together, these results show that the CXCR4 chemokine receptor is expressed by splenic cDCs, present in all three cDC subsets, and that the maturation state and CXCR4 expression within splenocytes from FLT-3 ligand-secreting tumor mice are comparable to naïve mice." (PMID 30489627, 2018). "Other reports have identified nuclear staining for CXCR4 in tumor cells and these findings correlated with improved prognosis, though when using different antibodies these results could not be replicated." (PMID 30257500, 2018). "In addition, F50067 was designed as an IgG1 monoclonal antibody, with Fc-mediated effector functions that would trigger both complement-dependent cytotoxicity (CDC) and antibody-dependent cellular cytotoxicity (ADCC) against CXCR4 expressing tumor cells." (PMID 29844860, 2018).
tumor (continued). "SDF-1/CXCR4 signaling has been shown to contribute to virtually all processes in tumor biology." (PMID 30622535, 2018). "In contrast to free oligo‐FdU, intravenous administration of T22‐GFP‐H6‐FdU selectively accumulates and internalizes in CXCR4+ cancer cells, triggering DNA damage and apoptosis, which leads to the selective depletion of CXCR4+ MetSCs and to reduced tumor formation and spheroid formation." (PMID 30190334, 2018). "Also, the interaction between CXCL12 and CXCR7 did influence CXCR4-mediated trans-endothelial migration of human tumor cells." (PMID 29977203, 2018). "High SDF-1/CXCL12 expression in tumours aids in the capture of CXCR4-expressing monocytes." (PMID 30504836, 2018). "Because CXCL12/CXCR4/CXCR7chemokine axis activation regulates the pattern of tumor growth and metastatic spread to organs expressing high levels of CXCL12, NOX-A12 was expected to be useful in the treatment of several types of cancers, including multiple myeloma, lung, colorectal and brain cancers." (PMID 29301363, 2018). "To examine how CXCR4 overexpression would impact on antitumor immunity, we evaluated graft-versus-tumor (GvT) responses mediated by allogeneic (B6, H-2b) T cells following transfer to tumor-bearing BALB/c (H-2d) recipients." (PMID 29485974, 2018). "Additionally, hypoxia induces the expression of CXCR4 on monocytes and macrophages, thereby highlighting a possible role of the CXCL12-CXCR4 axis for TAM trafficking to the hypoxic tumor areas." (PMID 30245686, 2018). "In summary, these preclinical in vivo and ex vivo data strongly suggest that SDF-1/CXCR4-mediated residency of tumor cells in stem cell niches induces resistance to chemo- and/or radiation therapy probably by inducing expression of a therapy-resistant cancer stem(-like) cell phenotype." (PMID 30622535, 2018). "Partial toxin‐induced depletion of FAP+ CAFs, as well as pharmacological blockage of CXCL12 signaling by inhibiting its receptor C‐X‐C chemokine receptor 4 (CXCR4), reduced tumor growth and enhanced T cell accumulation within the tumor, thus sensitizing tumors to α‐PDL1 treatment." (PMID 29280568, 2018). "In particular, for CXCR4 imaging, intratumoral hypoxia might have a great influence, as it is known that CXCR4 is strongly upregulated in hypoxic tumor regions." (PMID 30191351, 2018). "The ability of CD133+CXCR4+ CSCs to originate frank metastases when injected in humanized mice implanted with human bone stresses the prominent relevance of a conductive tumor microenvironment (with a pre-metastatic niche) to support tumor metastasis." (PMID 29461491, 2018). "Thus, membrane and/or cytoplasmic CXCR4 promotes tumor cell proliferation and metastasis, while nuclear CXCR4 is ineffective in explicating these functions." (PMID 29666622, 2018). "CXCR4 expression on tumor cells has been associated with a negative prognostic value for survival, homing to tissues with SDF-1 expression, resistance to angiogenesis inhibition and resistance to chemotherapy." (PMID 28402937, 2017). "Also here, patient overall survival was reduced when tumor vessels stained positive for CXCR4, although (probably due to the relatively small number of cases) statistical significance was not reached (log-rank test: p = 0.096)." (PMID 29282035, 2017). "Additionally, altered CXCR4 expression results in tumor growth, angiogenesis, invasion, and metastasis." (PMID 28182660, 2017). "In HCC tumor cells, frequency and intensity of expression of SSTRs and CXCR4 were only low." (PMID 29282035, 2017). "Although CXCR4 was not substantially expressed by HCC or CCC tumor cells, the distinct presence of CXCR4 on tumor capillaries in many cases may open up new possibilities to indirectly target such tumors by depriving them of their supportive environment." (PMID 29282035, 2017). "A different picture emerged regarding SSTR5 and CXCR4 expression in tumor capillaries." (PMID 29282035, 2017).